ZNF282 (zinc finger protein 282)
Description:
Binds to the U5 repressive element (U5RE) of the human T cell leukemia virus type I long terminal repeat. It recognizes the 5'-TCCACCCC-3' sequence as a core motif and exerts a strong repressive effect on HTLV-I LTR-mediated expression.
Synonyms: HUB1
Tractability: PROTAC: UniProt records ubiquitination sites on it; ubiquitination databases record sites on it.
Gene: Protein-coding gene on chromosome 7 (149,195,546 to 149,226,243, forward strand). Ensembl gene ENSG00000170265.
Subcellular location: Nucleus
Subcellular location (Human Protein Atlas): Nucleoplasm; Cytosol
Pathways (Reactome):
Gene expression (Transcription): Generic Transcription Pathway
Gene Ontology:
Molecular function: protein binding; sequence-specific double-stranded DNA binding; DNA-binding transcription factor activity; RNA polymerase II cis-regulatory region sequence-specific DNA binding; zinc ion binding
Biological process: negative regulation of DNA-templated transcription; regulation of DNA-templated transcription
Cellular component: nucleus
Genetic constraint (gnomAD): Loss-of-function variants: 26 observed, 56.37 expected, observed/expected ratio (o/e) 0.46, 90% interval 0.34 to 0.64. The upper end of that interval is the gene's LOEUF score, 0.64, which puts it in group 2 of 6, group 1 being the genes least tolerant of losing a copy. Missense variants: 782 observed, 868.64 expected, observed/expected ratio (o/e) 0.9, 90% interval 0.85 to 0.95. Synonymous variants: 392 observed, 369.61 expected, observed/expected ratio (o/e) 1.06, 90% interval 0.98 to 1.15.
Homologues: Orthologues: chimpanzee ZNF282 (99% identical), macaque ZNF212 (98% identical), dog ZNF282 (89% identical), mouse Zfp282 (89% identical), rat Zfp282 (89% identical), rabbit ZNF282 (86% identical), guinea pig ZNF282 (83% identical), zebrafish znf646 (16% identical), zebrafish si:dkey-89b17.4 (14% identical), Drosophila melanogaster mld (8% identical), zebrafish zgc:66472 (8% identical), zebrafish si:ch211-148l7.4 (7% identical). Paralogues in human: ZNF142 (17% identical), ZBTB24 (16% identical), ZNF574 (15% identical), ZFP92 (15% identical), ZNF160 (15% identical), ZNF420 (15% identical), ZNF84 (15% identical), ZNF91 (15% identical), ZNF48 (14% identical), ZNF107 (14% identical), ZNF208 (14% identical), ZNF665 (14% identical), and 24 more.
Diseases named in the same sentence as ZNF282 in open-access papers:
ZNF282 is named in the same sentence as 14 diseases in open-access papers, as found by Europe PMC text mining. Sharing a sentence is not in itself a finding about the gene and the disease. The quoted sentences say what the papers report.
breast carcinoma (3 papers, 2014 to 2025). "Zinc finger protein 282 (ZNF282) is a recently identified TF that is thought to play an oncogenic role in both breast cancer and esophageal cancer." (PMID 41331125, 2025). "In that report, we firstly presented essential roles of ZNF282 in migration, proliferation, and tumorigenicity of breast cancer cells." (PMID 25373738, 2014). "Recently, we have shown that ZNF282 interacts with estrogen receptor α (ERα) and functions as an ERα co-activator in breast cancer cells." (PMID 25373738, 2014). "Notably, ZNF282 interacts with estrogen receptor α (ERα) and functions as an ERα co-activator, promoting tumor progression in breast cancer." (PMID 41331125, 2025). "Therefore, our predicted gene ZNF282 can be regarded as an additional biomarker related to estrogen receptor for breast cancer subtyping." (PMID 31480430, 2019). "In addition to ZCCHC24, another zinc finger protein coding gene named ZNF282 has also been predicted as a potential distinctive marker for different breast cancer subtypes." (PMID 31480430, 2019). "Hence, the methylation status and expression pattern of ZNF282 may be different in breast cancers with high and low expression levels of estrogen receptor." (PMID 31480430, 2019).
COVID-19 (3 papers, 2022 to 2024). A disease caused by infection with severe acute respiratory syndrome coronavirus 2. "In addition, ZNF282 can be a repressor of COVID-19 RNA replication." (PMID 36298522, 2022). "Using published data, we use a set of optimized-performance COVID-19 genomic biomarkers (MND1, CDC6, ZNF282) to study the benefits and adverse effects of the BNT162b2 vaccine." (PMID 36366282, 2022).
esophageal squamous cell carcinoma (3 papers, 2014 to 2025). Esophageal squamous cell carcinoma (ESCC) is a type of esophageal carcinoma (EC) that can affect any part of the esophagus, but is usually located in the upper or middle third. "Another study has shown that ZNF282 is a co-activator of E2F1 in esophageal squamous cell carcinoma and promotes tumor progression." (PMID 41331125, 2025). "Mechanistically, ZNF282 functions as a critical coactivator of E2F transcription factor 1(E2F1), transcriptionally upregulating the expression of cyclin A1 (CCNA1) and cell division cycle 6 (CDC6), thereby driving malignant progression in esophageal squamous cell carcinoma (ESCC)." (PMID 41331125, 2025).
brain cancer (1 paper, 2014). A primary or metastatic malignant neoplasm affecting the brain. "In those studies, expressionof ZNF282 mRNA was higher in esophageal, tongue, colon, liver, pancreas, lung, urinary bladder, breast, brain cancer and melanoma samples than in normal samples, suggesting that ZNF282 might play an important role in growth and tumorigenesis of a variety of cancer cells." (PMID 25373738, 2014).
Cirrhosis (1 paper, 2019). A chronic disorder of the liver in which liver tissue becomes scarred and is partially replaced by regenerative nodules and fibrotic tissue resulting in loss of liver function. "In addition, we also found that MED24, FOXD2 and ZNF282 are associated with the progression from cirrhosis to HCC." (PMID 31811111, 2019).
gastric cancer (1 paper, 2023). A primary or metastatic malignant neoplasm involving the stomach. "Interestingly, the IL10+ Treg cluster also expressed high levels of PTMS, ZNF282, and TP63, which have been associated with oncogene activity and might help explain the association of H. pylori infection with the development of gastric cancer." (PMID 36810249, 2023).
leiomyosarcoma (1 paper, 2023). An uncommon, aggressive malignant smooth muscle neoplasm, usually occurring in post-menopausal women. "PORCUPINE highlighted genes and TFs that are enriched in driving heterogeneity among leiomyosarcoma patients, including RB1 and PPP2R1A as target genes, as well as the TFs E2F8 and ZNF282, which could potentially be inhibited." (PMID 37492373, 2023).
sarcoma (1 paper, 2023). A usually aggressive malignant neoplasm of the soft tissue or bone. "The role of ZNF282 (Zinc finger protein 282) in human cancers, including sarcomas, is unknown." (PMID 37492373, 2023).
tongue squamous cell carcinoma (1 paper, 2014). A squamous cell carcinoma that arises from the tongue. "In particular, expression of ZNF282 mRNA was significantly increased inESCC (two independent studies) and tongue squamous cell carcinoma and these results are very highly consistent with our result that ZNF282 expression is upregulated in ESCC." (PMID 25373738, 2014).
cancer (2 papers, 2014 to 2023). A tumor composed of atypical neoplastic, often pleomorphic cells that invade other tissues. "We also assessed the effect of ZNF282 depletion and overexpression on the function of cancer cells through in vitro and in vivoexperiments." (PMID 25373738, 2014). "Although these results suggest the possible role of ZNF282 in cancers, clinical significance and function of ZNF282 are completely unknown in most of cancers." (PMID 25373738, 2014). "The role of ZNF282 in human cancer has been very rarely studied except for our previous report." (PMID 25373738, 2014).
tumor (2 papers, 2014 to 2025). "Knockdown of ZNF282 significantly inhibited growth of TE9 ESCC cells (mean tumor volume : 3.33 mm3) compared to control group (mean tumor volume : 160.42 mm3) (p=0.009) (Figure." (PMID 25373738, 2014). "Our findings emphasize the importance of ZNF282 as a potential marker of tumor progression and its possible use in diagnosis, prognosis or development of therapeutic toolsagainst ESCC." (PMID 25373738, 2014). "This correlation between high ZNF282 expression and advanced T stage was more distinctly observed in the small size (<4cm) tumor group (p=0.0005)." (PMID 25373738, 2014). "We next investigated whether ZNF282 promotes tumor growth in in vivo model as well as in vitroexperiment." (PMID 25373738, 2014). "Because ZNF282 overexpression in ESCC is correlated with tumor invasiveness (advanced T stage), it is suspected that ZNF282 may enhance the invasive ability of tumor." (PMID 25373738, 2014). "Thus, we postulated that ZNF282, one of transcriptional coactivator, may also play an important role in tumor progression of ESCC." (PMID 25373738, 2014). "Thus, our results indicate that ZNF282 plays an important role in tumor progression of ESCC." (PMID 25373738, 2014). "This LINC02878/ZNF282/PYCR2 signaling cascade drives proline anabolism, thereby fueling tumor metabolic reprogramming and fostering aggressive malignant progression in CRC." (PMID 41331125, 2025). "Mechanistically, LINC02878 binds to the ZNF282 to activate PYCR2 expression, thereby enhancing proline biosynthesis and driving tumor aggressiveness." (PMID 41331125, 2025). "In order to determine the role of ZNF282 during tumor progression of ESCC, we designed shRNA against ZNF282 and confirmed that ZNF282 expression was greatly reduced by shRNA treatment (Figure." (PMID 25373738, 2014). "Because ZNF282 functions as a transcription co-activator of E2F1, which is a critical player in tumor progression, we investigated whether the prognostic effect of ZNF282 in ESCC was influenced by E2F1." (PMID 25373738, 2014). "Besides, we demonstrated that knockdown of ZNF282 induced apoptosis and cell cycle arrest as well as decreased migration, invasion, and tumorigenenicity in vitro,and inhibited growth of ESCC xenograft tumor in nude mice." (PMID 25373738, 2014).
ZNF282 also shares sentences with these, for which no sentence is quoted: colorectal cancer (1 paper); esophageal cancer (1); melanoma (1).